RN7SL311P (RNA, 7SL, cytoplasmic 311, pseudogene)
Gene: Miscellaneous RNA gene on chromosome 4 (139,185,441 to 139,185,746, forward strand). Ensembl gene ENSG00000265892.
Homologues: Orthologues: chimpanzee Metazoa_SRP (99% identical), macaque Metazoa_SRP (89% identical), guinea pig Metazoa_SRP (57% identical). Paralogues in human: RN7SL1 (80% identical), RN7SL2 (80% identical), RN7SL126P (79% identical), RN7SL3 (79% identical), RN7SL230P (77% identical), RN7SL479P (77% identical), RN7SL612P (77% identical), RN7SL664P (77% identical), RN7SL15P (76% identical), RN7SL186P (76% identical), RN7SL383P (76% identical), RN7SL45P (76% identical), and 703 more.